HSF1 (heat shock transcription factor 1)
Diseases named in the same sentence as HSF1 in open-access papers (continued):
Sharing a sentence is not in itself a finding about the gene and the disease.
cardiac hypertrophy (continued). "To identify the link between HSF1 and ischaemia‐related cardiac hypertrophy, we measured the expression and phosphorylation of HSF1 in cardiomyocytes in vivo and in vitro." (PMID 29992755, 2018). "HSF1 KO mice showed more significant maladaptive cardiac hypertrophy and deteriorated cardiac dysfunction 1 week after MI compared to WT MI mice." (PMID 29992755, 2018). "First, we identified HSF1 as an essential mediator of cardiac hypertrophy induced by hypoxic stimuli." (PMID 29992755, 2018). "Here, we have been suggested that heat‐shock transcription factor 1 (HSF1) is a novel repressor of ischaemia‐induced cardiac hypertrophy." (PMID 29992755, 2018). "In animal experiments, HSF1 TG mice showed alleviative cardiac fibrosis in response to pressure overload along with relived pathological cardiac hypertrophy and preserved cardiac function." (PMID 28091697, 2017). "Taken together, these findings uncovered that HSF1 overexpression is capable of suppressing pressure overload-induced cardiac fibrosis and maladaptive cardiac hypertrophy." (PMID 28091697, 2017). "The HSF1 KO mice also displayed a pronounced eccentric cardiac hypertrophy manifested by notably increased LVIDd, decreased LVEF, and preserved LVAWd compared with the WT mice." (PMID 28091697, 2017). "In addition to GATA, MEF2 and NFAT families, other transcription factors, such as UBF1 86, ATF3 87, T-Cdk9 88, XBP1 89, MITF 90, HSF1 91, C/EBP 92, KLF11 93 and KLF5/BTEB2 94 have been implicated in regulating cardiac hypertrophy." (PMID 39239522, 2024). "Furthermore, several important regulators involved in cardiac hypertrophy were focused including HSF-1, ATGL, RXRα, and ERRα." (PMID 35479323, 2022). "By upregulating expression of ALDH2 via mitochondrial import of PKCε while upregulating HSP90, HSF1 can play the protective role in response to myocardial hypertrophy injury resulting from pressure stimulation and further delay the occurrence and development of heart failure of mice." (PMID 32626739, 2020). "Through animal and cell experiments, we demonstrated the effect of HSF1 in promoting pressure-stimulated myocardial hypertrophy and further ameliorating heart failure by upregulating ALDH2 via PKC, providing a novel theoretical basis for exploring treatment approaches of heart failure." (PMID 32626739, 2020). "Whereas enhanced HSF1 activation inhibited the cardiac hypertrophy after MI in HSF1 TG mice." (PMID 29992755, 2018). "Finally, we revealed that enhanced HSF1 phosphorylation notably mitigated the pathological cardiac hypertrophy and inhibited the heart failure in the early stage of MI." (PMID 29992755, 2018). "Our data collectively demonstrated that HSF1 is critically involved in the pathological cardiac hypertrophy after MI via modulating JAK2/STAT3 signalling and may constitute a potential therapeutic target for MI patients." (PMID 29992755, 2018). "In summary, our study provides insights into the mechanisms of ischaemia‐induced cardiac hypertrophy and may have significant implications for the development of strategies for the treatment of MI through targeting of the HSF1." (PMID 29992755, 2018). "Given the reduced HSF1 phosphorylation in hypertrophic hearts under myocardial ischaemia, we next determined whether a decrease in HSF1 phosphorylation promotes hypoxia‐induced cardiac hypertrophy." (PMID 29992755, 2018). "We next explored whether the phosphorylation of HSF1 is necessary for the cardiac hypertrophy induced by MI." (PMID 29992755, 2018). "Our results showed that HSF2 positively regulated IGF-IIR transcription, which led to cardiac hypertrophy under hypertension-induced heart failure conditions, whereas HSF1 markedly inhibited IGF-IIR transcription to protect cardiomyocytes from hypertension-induced heart failure." (PMID 28796250, 2017).
cardiac hypertrophy (continued). "Second, to eliminate the possible compensatory or neuroendocrine factors which may influence the expression and phosphorylation of HSF1 in MI‐induced cardiac hypertrophy, NRCMs were isolated and stimulated with hypoxia, a well‐controlled experimental setting to mimic MI in an in vitro study." (PMID 29992755, 2018). "HSF1 protects cardiomyocyte from I/R injury and HSF1 phosphorylation, which is activated by angiotensin II (ANG II), resulting in cardiac hypertrophy." (PMID 31627188, 2019). "Upon MI, phosphorylated STAT3 was increased in the HSF1 KO mice, whereas inhibition of STAT3 phosphorylation ameliorated the ischaemia‐induced cardiac hypertrophy and cardiac dysfunction in mouse." (PMID 29992755, 2018). "We used mechanical stretch to establish the myocardial hypertrophy model and observed that HSF1/HSP70 and ALDH2 in the cardiomyocytes both recorded increased expressions, indicating that there exists a correlation between HSF1 and ALDH2." (PMID 32626739, 2020). "Additionally, we blocked PKC by using an inhibitor and observed that, when HSF1 was upregulated, the role of ALDH2 and the cardiac hypertrophy gene weakened." (PMID 32626739, 2020). "Therefore, we recommend a new molecular approach which illustrates that HSF1 and its target HIF‐1α/VEGF signalling pathway influences the exercise training‐activated cardioprotection against pressure overload–initiated cardiac hypertrophy." (PMID 31930683, 2020). "Additionally, ANG II activated ERK/glycogen-synthase kinase-3 (GSK3), phosphorylated heat shock transcription factor 1 (HSF1), resulting in a protein-coding gene RNF126 (ring finger protein 126) degradation for stabilizing IGF-IIR protein expression and leading to cardiac hypertrophy." (PMID 36359731, 2022). "Inhibition of HSP70 expression (both intracellular and extracellular) through inactivation of HSF-1 can promote myocardial hypertrophy and cardiac dysfunction but ameliorate cardiac fibrosis; functional inhibition of extracellular HSP70 using anti-HSP70 attenuates cardiac hypertrophy and fibrosis." (PMID 35115946, 2021). "Although our results might not exclude other mechanisms by which HSF1 suppresses cardiac hypertrophy induced by ischaemia, the inhibitory effect of HSF1 on the development of cardiac hypertrophy seems to be largely dependent on the repression of JAK2/STAT3 by HSF1." (PMID 29992755, 2018).
cervical carcinoma (13 papers, 2010 to 2025). A carcinoma arising from either the exocervical squamous epithelium or the endocervical glandular epithelium. "To elucidate the role of HSF1 in the 125I particle radiotherapy process for the treatment of cervical cancer, we silenced or overexpressed HSF1 in C33A cells and subjected them to 125I particle radiotherapy." (PMID 40399470, 2025). "Correlation analysis revealed that HSF1 is lowly expressed in cervical cancer, and ROS can promote the expression of HSF1, which in turn promotes the expression of PU.1 (SPI1), and PU.1 (SPI1) promotes the expression of Dectin1 (CLEC7A)." (PMID 40399470, 2025). "The results demonstrate that 125I seed radiotherapy significantly inhibits the invasion and migration of cervical cancer cells by upregulating the HSF1/PU.1/SYK signaling pathway." (PMID 40399470, 2025). "Finally, we used the subcutaneous xenograft tumor experiment in nude mice to verify that 125I particle radiotherapy inhibits the progression of cervical cancer by promoting the HSF1/PU.1/SYK signaling pathway." (PMID 40399470, 2025). "In addition, at least one microRNA (miRNA) has already been identified as a direct target of HSF1 in a human cervical cancer cell line." (PMID 35456403, 2022). "For example, the addition of anti forkhead box M1 (FOXM1) and heat shock factor (HSF1) aptamers to breast and cervical cancer cell lines showed the inhibition of their downstream transcriptional programs and led to impaired cell growth and apoptosis, respectively." (PMID 36358889, 2022). "To back up this approach and to correlate mere HSF1 activation to actual endogenous target gene expression, we included two further cell lines in our study to monitor Hsp expression: the human cervical carcinoma cell line HeLa and the human fibroblast cell line WI38." (PMID 35218516, 2022). "By generating a pSUPER-HSF1 vector, able to potently suppress HSF1 gene, they dramatically increased the sensitivity to hyperthermochemotherapy (combination of a Cisplatin treatment with heat-shock), leading to massive apoptosis of Hela cervical cancer cells." (PMID 24212658, 2011). "Microarray studies of mouse embryonic fibroblasts from wild-type and HSF1-null mice or a human cervical carcinoma cell line have shown that HSF1 controls only a subset of the genes altered by HS indicating that other inducible pathways play roles in regulating the Hsp genes." (PMID 20059764, 2010). "By upregulating the HSF1/PU.1/SYK signaling pathway, 125I seeds not only restrain the growth and proliferation of cervical cancer cells but also markedly diminish tumor invasion and migration." (PMID 40399470, 2025). "Metformin increased HSF-1, MICA and HSP70 protein expression in SiHa and HeLa cells and also induced MICA expression on the surface of human cervical cancer cells." (PMID 32631421, 2020). "In the present study, we found that metformin increased HSF-1, MICA and HSP70 protein expression in SiHa and HeLa cells and also induced MICA expression on the surface of human cervical cancer cells." (PMID 32631421, 2020).
cervical carcinoma (continued). "Therefore, we assessed HSF-1, HSP70 and MICA expression in cervical cancer cells after metformin treatment and also investigated the sensitivity of NK-92 cells to cancer cells." (PMID 32631421, 2020). "To test whether the HSF1 trimers that form upon treatment with PEITC are able to enhance transcription through heat shock elements (HSEs), we used the cervical cancer HeLa HSE-luciferase reporter cell line (HeLa-HSE-luc) stably transfected with the HSP70.1 promoter fused to the luciferase gene." (PMID 27354066, 2016). "Moreover, diminished HSPs expression resulting from HSF1 silencing did not abrogate resistance of cervix carcinoma HeLa cells to cisplatin." (PMID 24165036, 2013).
amyotrophic lateral sclerosis (12 papers, 2010 to 2025). Amyotrophic lateral sclerosis (ALS) is a neurodegenerative disease characterized by progressive muscular paralysis reflecting degeneration of motor neurons in the primary motor cortex, corticospinal tracts, brainstem and spinal cord. "This implies that the HSF1-mediated DNAJB2a/HSP70 heat shock response pathway is compromised in amyotrophic lateral sclerosis." (PMID 26936937, 2016). "DNAJC7 appears to be especially important in motor neurons, supported by its genetic link to amyotrophic lateral sclerosis (ALS) and recent evidence that loss of DNAJC7 in iPSC-derived motor neurons increases susceptibility to proteotoxic stress, in part due to impaired HSF1 signaling." (PMID 40832276, 2025). "A few HSF1 activators that work independently of Hsp90, like the natural antioxidant celastrol, the amyotrophic lateral sclerosis drug riluzole, and the antiulcer drug geranylreranylacetone, are less characterized mechanistically, but may be useful in the future for combinatorial regimens." (PMID 24523910, 2014). "In addition, increased expression of HSF1 and HSP70 helps to ameliorate pathologies of neurodegenerative diseases such as Huntington’s disease, Parkinson’s disease, and amyotrophic lateral sclerosis (ALS) in mouse and fly models." (PMID 31717493, 2019). "Additionally, we have demonstrated that the levels of HSF1 and heat shock proteins are significantly reduced in affected neuronal tissues from a TDP-43 transgenic mouse model of amyotrophic lateral sclerosis and patients with sporadic amyotrophic lateral sclerosis." (PMID 26936937, 2016). "In amyotrophic lateral sclerosis (ALS), the FDA-approved drug riluzole was reported to partly act by HSF-1 activation and amplification of the HSR." (PMID 20525284, 2010).
breast tumor (12 papers, 2011 to 2023). "Heat shock factor 1 (HSF1), a ubiquitously-expressed transcription factor, was also shown to be activated in breast CAFs, and loss of HSF1 in fibroblasts reduced xenograft breast tumor growth, as well as fibroblast production of TGF-β and SDF1." (PMID 26828520, 2016). "Phosphorylation of HSF1 at Thr120 is positively correlated with PIM2 and HSF1 expression in breast tumor samples." (PMID 36429128, 2022). "Delay in ERBB2/NEU (HER2)-induced breast tumor growth in Hsf1-/- mice may result from inhibited cell proliferation of mammary epithelial cells." (PMID 37894333, 2023). "Copy number alterations (CNA) of HSF1 were observed in 146 (15%) out of 962 breast tumors." (PMID 27713164, 2016). "Indeed, PIM2 may promote HSF1 protein stability via the ubiquitin proteasome pathway because the phosphorylation of HSF1 on Thr-120 has been shown to regulate both proteostasis and carboplatin induced-autophagy that promote breast tumor growth." (PMID 33854618, 2021). "Consistent with this prediction, upregulation C/EBPβ can induce acquisition of an invasive phenotype, and expression of HSF1 is required for cellular transformation and tumorigenesis in HER2-positive breast tumors." (PMID 21980275, 2011). "HSF1 is also required for cell transformation and tumorigenesis induced by the oncogene HER2 (Human Epidermal growth factor Receptor-2), which is responsible for aggressive breast tumors." (PMID 24212658, 2011). "HSF1 is also crucial for cell transformation and tumorigenesis induced by the human epidermal growth factor receptor-2 (HER2), an oncogene responsible for breast tumors aggressiveness." (PMID 24212658, 2011). "Furthermore, HSF1 was found required for the cell transformation and tumorigenesis induced by the ERBB2 (aka HER2) oncogene (see subsequent discussion of HER2 amplicon) responsible for aggressive breast tumors." (PMID 23468608, 2013).
liver cancer (12 papers, 2015 to 2025). An epithelial or non-epithelial malignant neoplasm that arises from the liver. "In liver cancer, the increased expression of HSF-1 in peritumoral tissue is associated with early recurrence." (PMID 29682483, 2018). "It has been reported that the increased level of HSF-1 is associated with a reduced survival outcome in human breast and liver cancer." (PMID 29682483, 2018). "Additionally, a high level of HSF1 was significantly associated with a low survival probability among liver cancer patients." (PMID 39248163, 2024). "HSF1 deduced liver cancer cell proliferation both in vitro and in vivo, partly through modulation of H3K27ac levels, influencing enhancer distribution." (PMID 40606603, 2025). "Taken together, these results strongly indicate that HSF1 plays a pivotal role in enhancing the proliferation of liver cancer cells, both in vitro and in vivo." (PMID 39248163, 2024). "In vitro and in vivo experiments were carried out to evaluate the impact of HSF1 on liver cancer cell proliferation." (PMID 39248163, 2024). "We next targeted HSF1 independently and analyzed its expression in different subsets of liver cancer patients, along with the relationship between its expression and patient prognosis." (PMID 39248163, 2024). "To explore how HSF1 regulates MYCN expression in liver cancer cells, we further investigated the regulatory mechanism of HSF1 on MYCN at the transcriptional level." (PMID 39248163, 2024). "HSF1 stimulates liver cancer cell proliferation both in vitro and in vivo, partly through modulation of H3K27ac levels, influencing enhancer distribution." (PMID 39248163, 2024). "HSF1 promotes an increased rate of glucose uptake and preferential production of lactate, known as Warburg effect, in breast and liver cancer cells by upregulating the lactate dehydrogenase enzyme via direct binding to the lactate dehydrogenase gene promoter." (PMID 38172561, 2024). "Taken together these results indicated that HSF1 promoted the proliferation of liver cancer cells by regulating MYCN." (PMID 39248163, 2024). "Through in vitro and in vivo experiments, we have demonstrated the capability of HSF1 to promote the proliferation of liver cancer cells." (PMID 39248163, 2024). "The results indicated that in conjunction with the downregulation of HSF1, MYCN expression was also downregulated, suggesting that MYCN is a downstream target of HSF1 in liver cancer cells." (PMID 39248163, 2024). "Based on the absorbance at 450 nm on the last day, liver cancer cell proliferation was significantly impaired after knockout of HSF1." (PMID 39248163, 2024). "In summary, our findings indicate that HSF1 functions not only as a transcription factor regulating gene transcription in liver cancer cells but also induces global changes in H3K27ac and alters the distribution of super enhancers." (PMID 39248163, 2024). "The result showed that there was a positive correlation between HSF1 expression and PD-L1 expression in liver cancer." (PMID 36482717, 2023). "Altogether, the present data indicate that HSF1 and c-Myc levels are directly correlated in human liver cancer." (PMID 29207593, 2017). "In particular, we determined the importance of HSF1 on v-Akt murine thymoma viral oncogene homolog (AKT)-induced liver cancer development in mice." (PMID 28903330, 2017). "Additionally, we utilized CUT&Tag, H3K27 acetylation enrichment, and RNA sequencing (RNA‐seq) to investigate the super‐enhancer (SE) regulatory landscapes of HSF1 in liver cancer cell lines." (PMID 39248163, 2024). "In order to investigate whether HSF1 promotes the proliferation of liver cancer cells by regulating MYCN, we designed and conducted a rescue experiment in Huh7 and MHCC97L cell lines." (PMID 39248163, 2024). "Thus, this concordant body of data indicates a reciprocal, positive regulation by HSF1 and c-Myc in human liver cancer cells." (PMID 29207593, 2017).